CTSF (cathepsin F)
Description:
Thiol protease which is believed to participate in intracellular degradation and turnover of proteins. Has also been implicated in tumor invasion and metastasis.
Synonyms: CATSF; CLN13
Tractability: Small molecule: a structure with a bound ligand is known; a high-quality ligand is known; it has a high-quality binding pocket; it belongs to a druggable protein family. Antibody: its Gene Ontology location is reachable by antibodies, with high confidence; UniProt predicts a signal peptide or a membrane-spanning region. PROTAC: ubiquitination databases record sites on it; its protein half-life has been measured; a small molecule that binds it is known.
Target class: Cysteine protease; Cysteine protease CA clan; Enzyme; Protease; Cysteine protease C1A family
Gene: Protein-coding gene on chromosome 11 (66,563,463 to 66,568,879, reverse strand). Ensembl gene ENSG00000174080.
Subcellular location: Lysosome
Subcellular location (Human Protein Atlas): Vesicles; Endoplasmic reticulum; Plasma membrane
Pathways (Reactome):
Immune System: MHC class II antigen presentation
Gene Ontology:
Molecular function: cysteine-type peptidase activity; protein binding; cysteine-type endopeptidase activity
Biological process: antigen processing and presentation of exogenous peptide antigen via MHC class II; proteolysis; immune system process
Cellular component: extracellular exosome; extracellular matrix; extracellular vesicle; lysosomal lumen; lysosome; cytoplasm; intracellular organelle lumen
Genetic constraint (gnomAD): Loss-of-function variants: 65 observed, 61.66 expected, observed/expected ratio (o/e) 1.05, 90% interval 0.86 to 1.3. The upper end of that interval is the gene's LOEUF score, 1.3, which puts it in group 5 of 6, group 1 being the genes least tolerant of losing a copy. Missense variants: 641 observed, 598.07 expected, observed/expected ratio (o/e) 1.07, 90% interval 1 to 1.14. Synonymous variants: 256 observed, 232.22 expected, observed/expected ratio (o/e) 1.1, 90% interval 1 to 1.22.
Gene-disease validity (ClinGen):
ClinGen rates the evidence that CTSF causes each of these diseases.
adult neuronal ceroid lipofuscinosis (autosomal recessive): Definitive. A genetically heterogeneous group of neuronal ceroid lipofuscinoses (NCLs) with onset during the third decade of life, characterized by dementia, seizures and loss of motor capacities, and sometimes associated with visual loss caused by retinal degeneration.
Homologues: Orthologues: chimpanzee CTSF (99% identical), macaque CTSF (85% identical), dog CTSF (79% identical), mouse Ctsf (75% identical), guinea pig CTSF (74% identical), pig CTSF (73% identical), rat Ctsf (73% identical), rabbit CTSF (71% identical), zebrafish ctsf (46% identical), tropical clawed frog ctsf (45% identical), Caenorhabditis elegans tag-196 (35% identical), Drosophila melanogaster CtsF (34% identical), and 27 more. Paralogues in human: CTSW (28% identical), CTSL (23% identical), CTSV (23% identical), CTSH (22% identical), CTSK (21% identical), CTSO (20% identical), CTSS (20% identical), CTSC (18% identical), CTSZ (14% identical), CTSB (13% identical), TINAGL1 (13% identical), TINAG (12% identical).
Diseases named in the same sentence as CTSF in open-access papers:
CTSF is named in the same sentence as 64 diseases in open-access papers, as found by Europe PMC text mining. Sharing a sentence is not in itself a finding about the gene and the disease. The quoted sentences say what the papers report.
gastric cancer (8 papers, 2021 to 2025). A primary or metastatic malignant neoplasm involving the stomach. "CTSF is also associated with tumor growth, invasion, and metastasis, which is identified as a marker of cervical and gastric cancers." (PMID 39925015, 2025). "Recently, it has been suggested that a panel of serum biomarkers including CTSF could serve as a prognostic and diagnostic tool to predict survival in gastric cancer (GC) patients." (PMID 38891048, 2024). "CTSF regulates BCL2 expression, and the dysfunction of CTSF promote the proliferation of gastric cancer cells." (PMID 39925015, 2025). "In gastric cancer, it has been shown that CTSF is involved in the growth and apoptosis where CTSF knockdown promotes proliferation by inhibiting apoptosis." (PMID 35286517, 2022). "CTSF expression is downregulated in gastric cancer cells and tissues, and CTSF knockdown significantly suppressed gastric cancer cell apoptosis." (PMID 34372921, 2021). "Similarly, gastric cancer exhibits notable reduction of CTSF levels in both cellular models and clinical tissue samples." (PMID 40381082, 2025). "Recently, CTSF has been identified as a marker of cancer cells in cervical and gastric cancers." (PMID 36057013, 2023). "LINC00982 can bind to the transcription factor HEY1 and inhibit its expression, and then promote the expression of CTSF by blocking the binding of HEY1 to the CTSF promoter, thus blocking the progression of gastric cancer." (PMID 35771155, 2022).
breast carcinoma (6 papers, 2012 to 2025). "Their finding that CTSF is causally linked to breast cancer supports our results and highlights the role of cathepsins in the disease." (PMID 39944834, 2025). "In ER-positive breast cancer, CSK (OR = 0.955, p = 0.038) and CTSF (OR = 1.125, p < 0.001) maintained the same causal trends as observed in breast cancer." (PMID 38304232, 2023). "Specifically, PEX14 (OR = 1.201, p = 0.016) and CTSF (OR = 1.114, p < 0.001) both displayed positive and causal association with breast cancer." (PMID 38304232, 2023). "Among the “Strong” Tiers, PEX14 (Z = 4.839) and CTSF (Z = 3.681) had a positive association with breast cancer." (PMID 38304232, 2023). "For instance, one study performed MR analysis on a single cohort of 732 plasma proteins, where GDI2 and CTSF were identified as potential targets for breast cancer, aligning with our research." (PMID 38304232, 2023). "Overall, we found 5 proteins (PEX14, CTSF, SNUPN, CSK, PARK7) with strong causal links to breast cancer." (PMID 38304232, 2023). "A recent study reported that CTSF may act as an independent poor prognostic factor for basal-like breast cancer." (PMID 38304232, 2023). "Additionally, another study also suggested that CTSF could be a potential therapeutic target for breast cancer, further emphasizing the importance of cathepsins as targets for future drug development." (PMID 39944834, 2025). "Therefore, CTSF as a potential therapeutic target for breast cancer is credible." (PMID 38887235, 2024). "Additionally, CSK and CTSF followed the same trends with the findings from breast cancer." (PMID 38304232, 2023). "Similarly, GDI2 (OR: 0.85, 95% CI 0.80–0.91), ISLR2 (OR: 0.87, 95% CI 0.82–0.93), and CTSF (OR: 1.14, 95% CI 1.08–1.21) could potentially be targets for breast cancer." (PMID 37735436, 2023). "We found that ANXA2R protects against in situ breast cancer by reducing the expression of cathepsin F. PRX and CRY2 are protective factors for both cathepsin Z and in situ breast cancer." (PMID 39944834, 2025). "Research indicates that Cathepsin F may be associated with the development and progression of certain tumors, such as lung cancer, thyroid cancer, and cervical cancer, although there is a lack of studies investigating its relationship with breast cancer." (PMID 38887235, 2024). "We also compared the expression intensities of PRSS23, CTSC, CTSF, and MMP-24 from 52 ERα-positive breast cancer specimens within the van't Veer dataset." (PMID 22291950, 2012). "Cathepsin F can mediate the effects of ANXA2R and ZNF605 on in situ breast cancer." (PMID 39944834, 2025).
neuronal ceroid lipofuscinosis (6 papers, 2010 to 2024). "CTSF (cathepsin F), implicated here for depression and bipolar disease, is a lysosomal protein which is involved in the pathogensis of some types of neuronal ceroid lipofuscinosis." (PMID 36504281, 2023). "In mice, Cathepsin F deficiency leads to phenotypes resembling late onset neuronal ceroid lipofuscinosis (NCL)." (PMID 20388210, 2010). "Mutations in CTSF/CLN13, encoding cathepsin F, have recently been reported in Kufs disease (KD) type B (MIM 606725), an autosomal recessive, adult-onset, neuronal ceroid lipofuscinosis (NCL)." (PMID 26141065, 2015). "The clinical traits of Kufs disease (KD) type B (CLN13), an adult-onset neuronal ceroid lipofuscinosis (NCL), are well established according to the neurological features of the cases reported with mutations in CTSF." (PMID 26141065, 2015).
Kufs disease type B (5 papers, 2018 to 2025). "Several studies in recent years have shown a correlation between novel variants in the CTSF gene and neurodegenerative disorders, including dementia, early- and late-onset Alzheimer’s disease (AD), and Kufs disease type B." (PMID 38891048, 2024). "Later, the CLN13 form was studied in families with Kufs disease type B and mutations in CTSF were linked to an ANCL form." (PMID 37573956, 2023). "CLN13 disease, also known as Kufs disease type B, is caused by mutations in CTSF." (PMID 39925015, 2025). "In addition, a novel homozygous frameshift pathogenic variant p.Gly439Alafs*36 in the CTSF gene was identified that causes Kufs disease type B while mimicking frontotemporal dementia–parkinsonism." (PMID 38891048, 2024). "Mutation of cathepsin F (CTSF) is correlated with type B Kufs disease and Alzheimer’s disease." (PMID 35494076, 2022).
dementia (4 papers, 2018 to 2025). Loss of intellectual abilities interfering with an individual's social and occupational functions. "We believe that loss of CTSF causes a neurodegenerative disorder with a broad phenotypic spectrum that primarily presents with dementia." (PMID 34561610, 2021). "Now, we know that Kufs disease with progressive myoclonus epilepsy (type A) is associated with mutations in the CLN6 gene, while Kufs disease with dementia and motor disturbances (type B) is linked to mutations in the CTSF gene (also known as CLN13)." (PMID 39925015, 2025). "From this study, we can speculate that CTSF screening could represent a marker of early-onset dementia limiting the need for invasive biopsies." (PMID 38891048, 2024).
lung carcinoma (4 papers, 2022 to 2025). "For example, recent findings demonstrate that secretory proteins such as Cathepsin F and Fibulin-1 serve as novel circulating diagnostic biomarkers, enabling early detection and clinical monitoring of brain metastases in lung cancer patients." (PMID 40225580, 2025). "We also sought to establish a prediction model for early detection of BM in patients with lung cancer based on the CTSF and FBLN1." (PMID 35217799, 2022). "We further explored the value of CTSF as a biomarker for therapeutic monitoring and prognostic assessment of patients with lung cancer BM." (PMID 35217799, 2022). "ROC curve analysis was used to evaluate the performance of CTSF and FBLN1 as serum biomarkers for diagnosing NSCLC BM, compared with the classical serum biomarkers for lung cancer (CEA, CA125, SCC, CYFRA211)." (PMID 35217799, 2022).
brain tumors (3 papers, 2022 to 2025). "Thirdly, on ROC curve analysis, a combination of CTSF and FBLN1 was found to effectively discriminate NSCLC BM cases from NSCLC and primary brain tumours cases." (PMID 35217799, 2022). "The clinical value of CTSF, FBLN1, and AKR1B10 in the diagnosis of NSCLC BM was assessed in cohort 2 comprising of 459 patients including 379 patients with NSCLC, 30 primary brain tumours (PBT), and 50 HG." (PMID 35217799, 2022). "CTSF was not commonly expressed in lung tissues and other brain tumours." (PMID 35217799, 2022). "Song Wei and associates identified that the concentrations of cathepsin F (CTSF) and Fibulin-1 are elevated in the serum and tissue of non-small cell lung cancer (NSCLC) patients with brain metastases, in contrast to patients without brain metastases or individuals with primary brain tumors." (PMID 39791166, 2025). "Secondly, the expressions of CTSF and FBLN1 in NSCLC BM tissues were significantly higher than those in NSCLC without BM and other primary brain tumour tissues, although the expression of FBLN1 in tumour cells was relatively weak." (PMID 35217799, 2022).
cervical cancer (3 papers, 2005 to 2025). A primary or metastatic malignant neoplasm involving the cervix. "In cervical cancer, studies have found that CTSF gene expression is markedly upregulated, and its reliability has been validated using endpoint RT-PCR technology." (PMID 40381082, 2025). "Our results are in agreement with a previous study which revealed high levels of CTSF in HeLa cells, but it has not been described in cervical cancer." (PMID 15989693, 2005). "In conclusion, our results show that CTSF, MMP11 and 12 are expressed in dysplastic and tumoral epithelial cells suggesting all of these proteins could be used as "potential" progression markers for cervical cancer." (PMID 15989693, 2005).
Kufs disease (3 papers, 2020 to 2025). "Mutations in the CTSF gene result in NCL type 13 (CLN13, OMIM ID: 615362), an adult-onset form of NCL, also known as type B Kufs disease." (PMID 32326609, 2020).
radiation-induced dermatitis (3 papers, 2021 to 2024). "Regarding anti-apoptotic action, it was shown that ASCs protect against radiation-induced dermatitis by exerting an anti-apoptotic effect through inhibition of cathepsin F (CTSF) expression." (PMID 35565514, 2022). "ADSCs protect against radiation-induced dermatitis by exerting an anti-apoptotic effect through inhibition of CTSF expression." (PMID 34372921, 2021). "ADSCs protect against radiation-induced dermatitis, have an anti-apoptotic effect by suppressing CTSF expression, and may be a promising therapeutic candidate for the prevention of radiation-induced dermatitis." (PMID 38891048, 2024). "ADSCs protect against radiation-induced dermatitis, exhibit an anti-apoptotic effect by inhibiting CTSF expression, and may be a good therapeutic candidate to prevent the development of radiation-induced dermatitis." (PMID 34372921, 2021). "Furthermore, ADSCs downregulated cathepsin F expression in a rat model of radiation-induced dermatitis." (PMID 34372921, 2021). "However, whether CTSF is involved in the pathogenesis of radiation-induced dermatitis is unclear." (PMID 34372921, 2021).
thyroid cancer (3 papers, 2024 to 2025). "Additionally, immunohistochemical analysis of thyroid cancer tissue samples indicated that the expression of CTSF in patients with the mutation was higher compared to those with the wild-type gene and the surrounding non-cancerous tissue." (PMID 39791166, 2025). "Thyroid cancer manifests as a distinct type of malignancy characterized by significant expression of CTSF." (PMID 38891048, 2024). "This analysis revealed significantly increased immunoreactivity of the mutated CTSF gene in PTC tissue compared to healthy tissue, highlighting the potential role of CTSF variations as a predictive factor for PTC inheritance and thyroid cancer inheritance in general." (PMID 38891048, 2024).
age-related macular degeneration (2 papers, 2024). Age-related loss of vision in the central portion of the retina (macula), secondary to retinal degeneration. "Cathepsins are lysosomal proteases and susceptible to age-related alterations, while CTSF has also been reported to work as a causal factor for age-related macular degeneration." (PMID 39007149, 2024). "Research has confirmed a causal relationship between early age-related macular degeneration (AMD) and elevated serum CTSF levels." (PMID 38891048, 2024).
clear cell renal cell carcinoma (2 papers, 2024 to 2025). "Studies show that CTSF expression is significantly reduced at both mRNA and protein levels in clear cell renal cell carcinoma (ccRCC), which correlates with poor clinical outcomes." (PMID 40381082, 2025).
Parkinsonism (2 papers, 2020 to 2022). Characteristic neurologic anomaly resulting from degeneration of dopamine-generating cells in the substantia nigra, a region of the midbrain, characterized clinically by shaking, rigidity, slowness of movement and difficulty with walking and gait. "From all the reported associated cases, parkinsonism was reported in ANCL type B and was associated with mutations in the CTSF gene." (PMID 35462699, 2022).
skin aging (2 papers, 2023 to 2025). The gradual irreversible changes in structure of skin that occur as a result of the passage of time.. "Cathepsin F (CTSF) is associated with skin aging and serves as a potential specific marker for fibroblasts and keratinocytes in aged skin." (PMID 40941372, 2025).
acute promyelocytic leukemia (1 paper, 2021). An aggressive form of acute myeloid leukemia (AML), characterized by arrest of leukocyte differentiation at the promyelocyte stage, due to a specific chromosomal translocation t(15;17) in myeloid cells. "Among the three overexpressed proteins for high Ara-C LC50 level, CTSF was shown to have a function in azurophil granules and was found to be overexpressed in acute promyelocytic leukemia (APL) FLT3-ITD." (PMID 34202615, 2021).
amyotrophic lateral sclerosis (1 paper, 2025). Amyotrophic lateral sclerosis (ALS) is a neurodegenerative disease characterized by progressive muscular paralysis reflecting degeneration of motor neurons in the primary motor cortex, corticospinal tracts, brainstem and spinal cord. "CTSF and MFSD8 (CLN7) are involved in the lysosomal–autosomal pathway that contributes to amyotrophic lateral sclerosis (ALS)/FTD." (PMID 39925015, 2025).
aneurysm (1 paper, 2019). Bulging or ballooning in an area of an artery secondary to arterial wall weakening. "Furthermore, AngII treatment of macrophages stimulated increased production of cathepsin F, which may specifically compensate for cathepsin K in AngII-induced aneurysms compared to the elastase model." (PMID 31546645, 2019).
basal cell carcinoma (1 paper, 2024). A carcinoma involving the basal cells. "In the MR study, we found that tissue protease L2 can promote skin cancer, Cathepsin O, and Cathepsin F are associated with an increased risk of basal cell carcinoma." (PMID 39312365, 2024).
Batten disease (1 paper, 2022). "Commonly known as Batten disease, the different subtypes are each caused by a mutation in a distinct ceroid lipofuscinosis neuronal (CLN) gene (PPT1/CLN1, TPP1/CLN2, CLN3, DNAJC5/CLN4, CLN5, CLN6, MFSD8/CLN7, CLN8, CTSD/CLN10, PGRN/CLN11, ATP13A2/CLN12, CTSF/CLN13)." (PMID 35252181, 2022).
behavioral disorders (1 paper, 2022). "In adults with nonspecific mental, motor, or behavioral disorders, in whom NCL is suspected, the first line of testing includes the just-mentioned enzymatic tests for PPT1, TTP1, CTSD, and CTSF, which, when normal, should prompt the clinician to perform ultrastructural testing." (PMID 35628533, 2022).
bipolar disorder (1 paper, 2023). A disorder of the brain that causes unusual shifts in mood, energy, activity levels and the ability to carry out day-to-day tasks. "CTSF was associated with one pQTL (rs572846) and had shared effects with bipolar disorder and depression." (PMID 36504281, 2023).
bone cancer (1 paper, 2023). A primary or metastatic malignant neoplasm affecting the bone or articular cartilage. "CTSF has been documented to be used in the treatment of bone cancer and chronic obstructive pulmonary disease." (PMID 38304232, 2023).